PPP1R14C (protein phosphatase 1 regulatory inhibitor subunit 14C)
Description:
Inhibitor of the PP1 regulatory subunit PPP1CA.
Synonyms: KEPI; CPI17-like; NY-BR-81
Tractability: Antibody: UniProt places it where antibodies can reach, with medium confidence. PROTAC: its protein half-life has been measured.
Gene: Protein-coding gene on chromosome 6 (150,143,044 to 150,250,392, forward strand). Ensembl gene ENSG00000198729.
Subcellular location: Cytoplasm; Membrane
Gene Ontology:
Molecular function: protein serine/threonine phosphatase inhibitor activity; phosphatase inhibitor activity; protein phosphatase regulator activity
Cellular component: cytoplasm; membrane
Genetic constraint (gnomAD): Loss-of-function variants: 12 observed, 10.55 expected, observed/expected ratio (o/e) 1.14, 90% interval 0.73 to 1.76. The upper end of that interval is the gene's LOEUF score, 1.76, which puts it in group 6 of 6, group 1 being the genes least tolerant of losing a copy. Missense variants: 159 observed, 148.07 expected, observed/expected ratio (o/e) 1.07, 90% interval 0.94 to 1.23. Synonymous variants: 62 observed, 61.83 expected, observed/expected ratio (o/e) 1, 90% interval 0.82 to 1.24.
Homologues: Orthologues: chimpanzee PPP1R14C (99% identical), macaque PPP1R14C (98% identical), pig PPP1R14C (94% identical), dog PPP1R14C (93% identical), rat Ppp1r14c (92% identical), mouse Ppp1r14c (91% identical), tropical clawed frog ppp1r14c (66% identical), zebrafish ppp1r14c (57% identical), Drosophila melanogaster CG17124 (24% identical), Caenorhabditis elegans F55C10.5 (19% identical). Paralogues in human: PPP1R14B (53% identical), PPP1R14A (33% identical), PPP1R14D (28% identical).
Diseases named in the same sentence as PPP1R14C in open-access papers:
PPP1R14C is named in the same sentence as 8 diseases in open-access papers, as found by Europe PMC text mining. Sharing a sentence is not in itself a finding about the gene and the disease. The quoted sentences say what the papers report.
breast carcinoma (2 papers, 2022 to 2023). "The expression and clinical significance of PPP1R14C were then assessed by immunohistochemistry (IHC) and survival analysis in 150 breast cancer patient specimens, including 50 non‐TNBCs and 100 TNBCs." (PMID 35090098, 2022). "PPP1R14C was exogenously transduced or endogenously silenced in two human breast cancer cell lines (MDA‐MB‐231 and SUM159PT)." (PMID 35090098, 2022). "Although some studies reported that PPP1R14C was down‐regulated in some breast cancer cells, we discovered that PPP1R14C was detectable in all breast cancer subtypes and was specifically overexpressed in TNBC, which was supported by both GEO and TCGA datasets." (PMID 35090098, 2022). "Meanwhile, PPP1R14C was highly expressed in basal‐like breast cancer (BLBC), followed by normal tissues and other subtypes (Luminal A, Luminal B, and HER‐2)." (PMID 35090098, 2022). "Two genes upregulated in tumors from all races and with a role in tumorigenesis were PPP1R14C, which was shown to promote breast cancer cell proliferation, maintaining GSK3 in an inactive state in triple-negative breast cancer, and EGFL6, which regulates angiogenesis and tumor growth." (PMID 37686244, 2023). "Furthermore, the role of PPP1R14C in metastasis was explored in an orthotopic mouse model of spontaneous breast cancer metastasis using the 4T1 cells." (PMID 35090098, 2022). "To identify which PKC family member might regulate PPP1R14C in TNBC, we analysed PKC genes expression in the TCGA breast cancer dataset." (PMID 35090098, 2022).
prostate carcinoma (2 papers, 2018 to 2023). A carcinoma that arises from epithelial cells of the prostate gland. "For instance, PPP1R14C, an E2F1 target, which encodes a regulatory inhibitor subunit of protein phosphatase 1 and promotes cell-cycle progression and migration in prostate cancer cells, was specifically activated by the K450/451R mutant." (PMID 37663929, 2023).
tumor (5 papers, 2018 to 2023). "Tumours with overexpression of PPP1R14C had a high level of Ki‐67, whereas the PPP1R14C‐silenced tumours showed decreased Ki‐67 levels." (PMID 35090098, 2022). "Compared with the control groups, tumour growth was remarkably accelerated in the PPP1R14C‐overexpressing group, or suppressed in the PPP1R14C‐silenced group." (PMID 35090098, 2022). "We further investigated whether inhibition of GSK3β was essential for the tumour‐promoting functions of PPP1R14C in TNBC." (PMID 35090098, 2022). "Thus, PPP1R14C promotes the aggressiveness, tumour growth, and metastasis of TNBC cells in vitro and in vivo by sustaining inactive GSK3β." (PMID 35090098, 2022). "Importantly, our real‐time PCR and western blotting analyses did show that PPP1R14C was robustly upregulated in TNBC tumour tissues and cell lines." (PMID 35090098, 2022). "Furthermore, the clinical expression of MLCP components could suggest diminished MLCP activity may play a role in tumour metastasis, and as such we sought to investigate the role of PPP1R14C in cell migration." (PMID 29423094, 2018). "Our present data revealed that PPP1R14C, together with PRKCI, and PP1, maintained the phosphorylation of GSK3β at Ser9, which accelerated tumour proliferation and metastasis in TNBC." (PMID 35090098, 2022). "The results showed that the expression of ACACB, ATP8B4, C14orf28, CIRBP, and DTWD1 were higher in normal tissues, and the content of CDC6, DSP, HMGB3, HNRNPA3P1, PPP1R14C, and TPX2 were higher in tumor tissues." (PMID 35778922, 2022). "Moreover, similar tumour‐promoting effects were also observed when using a mouse‐derived TNBC cell line 4T1, suggesting that the role of PPP1R14C was conserved." (PMID 35090098, 2022).
cancer (2 papers, 2022 to 2025). A tumor composed of atypical neoplastic, often pleomorphic cells that invade other tissues. "Importantly, inhibition of PPP1R14C phosphorylation showed the anti‐cancer activity." (PMID 35090098, 2022).
PPP1R14C also shares sentences with these, for which no sentence is quoted: hepatocellular carcinoma (1 paper); leiomyoma (1); leukaemia (1); triple-negative breast carcinoma (1).